CRP (C-reactive protein)
Diseases named in the same sentence as CRP in open-access papers (continued):
Sharing a sentence is not in itself a finding about the gene and the disease.
cardiovascular disease (continued). "However, it was positively associated with CRP, an inflammatory marker and independent predictor of cardiovascular disease." (PMID 22984471, 2012). "In addition, AoAC progression along with previous history of cardiovascular disease and hs-CRP levels was found to be significantly associated with all-cause and cardiovascular mortality in univariate Cox analysis." (PMID 23144974, 2012). "Several studies have shown that elevated levels of CRP are directly associated traditional cardiac risk factors and independently increase the risk of cardiovascular disease and mortality in both healthy individuals and patients with existing cardiovascular disease." (PMID 23198160, 2012). "Once these steps are completed, we could assess whether the salivary CRP test has the potential to be a non-invasive and practical clinical tool to monitor risk for cardiovascular diseases in large populations." (PMID 22152006, 2011). "C Reactive Protein (CRP), an acute phase protein synthesized primarily by the liver, is the most widely used biomarker of inflammation and is also a powerful risk marker for cardiovascular diseases." (PMID 21029457, 2010). "Since an increased CRP is a risk factor for cardiovascular diseases, the pathogenesis of both processes may possibly start with an increased systemic inflammation." (PMID 20167091, 2010). "The median CRP concentration of 3.7 mg/L was above the high-risk level for cardiovascular disease." (PMID 20123638, 2010). "Previous studies reported high C-reactive protein (CRP) levels in Indigenous Australians, which may contribute to their high risk of cardiovascular disease." (PMID 21078191, 2010). "PTX3 is, in contrast with CRP, highly conserved between mice and humans and might therefore be associated with cardiovascular disease in COPD." (PMID 20920344, 2010). "Similarly, the NHANES study found that after adjusting for traditional cardiovascular disease risk factors, patients with highest quartile of CRP had a 2.1-fold increased odds for PAD." (PMID 20307322, 2010). "The decrease in plasma CRP levels after cherry intake suggests a reduction in inflammation that may affect the risk for cardiovascular diseases." (PMID 20944519, 2010). "Indeed, an association between cardiovascular disease and systemic markers of inflammation, including C-reactive protein, IL-6, homocysteine, white blood cell count, D-Dimer formation, factor VIII, has been demonstrated." (PMID 20339564, 2009). "These cytokines play an important role in the induction of CRP which may facilitate, directly or indirectly, the formation of atherosclerotic plaques leading to an increased risk for cardiovascular diseases." (PMID 19240794, 2009). "In a population with an increased risk of T2D and cardiovascular disease, however, improvement in flow-mediated vasodilation and reduction of serum C-reactive protein (CRP), a risk factor for cardiovascular disease, are prominent only in Ala12 allele carriers, but not in Pro12 homozygotes." (PMID 19390629, 2009). "CRP and IL-6 may contribute, in part, to the observed associations between chronic infections and cardiovascular diseases." (PMID 20407653, 2009). "The pro-inflammatory effects of CRP may explain the increased risk of developing cardiovascular disease (CVD) associated with persistently elevated baseline CRP levels." (PMID 19426506, 2009). "CRP is a known marker of cardiovascular disease risk and levels in COPD are associated with mortality, leading to the hypothesis that CRP levels are indicative of cardiovascular disease risk in COPD patients." (PMID 19480658, 2009). "A speculative interpretation of our study would be that women being confident, optimistic and self-sufficient, by displaying lower levels of CRP, also may exhibit a decreased risk for cardiovascular disease." (PMID 18384670, 2008). "In addition, it is well appreciated that IL-6 induces hepatic CRP production, which is an independent risk marker of cardiovascular disease." (PMID 19936194, 2008).
cardiovascular disease (continued). "CRP also has demonstrated utility as a predictive marker of future risk of cardiovascular disease." (PMID 18445267, 2008). "CRP being associated with certain personality traits, and, at the same time, being an important risk factor for cardiovascular disease, makes it tempting to suggest that it may serve as a mediator between these two variables." (PMID 18384670, 2008). "Finally, this study evaluated the effect of PSE on CRP, a proposed risk factor in cardiovascular disease." (PMID 17419879, 2007). "Also, when combined with CRP, it could be a useful predictor of the risk of death from cardiovascular disease." (PMID 40821848, 2025). "Given the widespread use of high-sensitivity CRP (hsCRP) assays, which detect lower CRP concentrations than standard assays, numerous epidemiological studies have shown that hsCRP serves as a valuable marker for predicting the risk of cardiovascular disease (CVD)." (PMID 40290053, 2025). "Given that systemic inflammation, and in particularly CRP, is a biomarker strongly association with cardiovascular disease, these findings provide insight in the mechanisms by which initiation of ART during primary infection in people living with HIV may improve health outcomes." (PMID 38976697, 2024). "Longitudinal studies are essential to determine whether an increase in blood counts within the reference range during adolescence may serve as an early indicator of future risk of developing cardiovascular diseases as similarly documented for an increase in CRP levels." (PMID 38255379, 2024). "Furthermore, studies have implicated adverse effects of CRP on endothelial cell health and function, including decreased endothelial fibrinolytic capacity and endothelium-dependent vasodilation, which can contribute to cardiovascular disease development." (PMID 39301363, 2024). "Furthermore, the relationship between CRP and AD risk may be largely confounded by cardiovascular disease (CVD), which is highly associated with peripheral CRP level." (PMID 37593375, 2023). "However, the mean hs-CRP level was in the range of average risk for cardiovascular disease." (PMID 37148328, 2023). "Moreover, CRP has been linked with cardiovascular disease in general population." (PMID 37762312, 2023). "Within females, basal CRP levels greater than 1 mg L−1 are suggested to increase the risk of endothelial damage, myocardial infarction, thromboembolic events, and atrial fibrillation and have been used as a clinical threshold to determine cardiovascular disease risk." (PMID 37487629, 2023). "Consequently, professional periodontal therapy could decrease the CRP levels and potentially lower the risk of cardiovascular disease." (PMID 36316604, 2023). "Cardiovascular diseases are the main cause of worldwide mortality, affecting a large part of the older population, with high prevalence in women since the cardiovascular disease risk factors (e.g., C-reactive protein, triglycerides, LDL-c) appear to be exacerbated by the menopause." (PMID 36673920, 2023). "Moreover, in a study regarding the “high-sensitivity C-reactive protein (hs-CRP),” a marker of inflammation which could act as a predictor of cardiovascular disease, researchers found that dual users had the highest risk of having elevated CRP levels." (PMID 36324451, 2022). "Considering the increases of the cardiovascular risk markers IL-6, SAA, and CRP after controlled exposure to zinc and/or copper-containing welding fumes, our finding of elevated levels of CDR1as adds another potential risk marker for cardiovascular diseases after exposure to Zn/Cu metal particles." (PMID 35915466, 2022). "In addition to being prevalent in inflammation, CRP also plays a key role in endothelial dysfunction, atherosclerosis and cardiovascular diseases, having been recognized as a risk predictor of cardiovascular diseases and a risk predictor of pulmonary arterial diseases." (PMID 35911521, 2022).
cardiovascular disease (continued). "Therefore, monitoring the concentration of CRP in the body and quantifying the amounts may help reduce and predict the risk of cardiovascular disease (CVD) (Sonuç Karaboğa and Sezgintürk, 2018)." (PMID 34150714, 2021). "There are many common molecular signaling pathways between COPD and OSA, such as C-reactive protein, interleukin 6, and nuclear factor kappa B. Their interaction can cause a systemic inflammatory response and increase body oxidative stress, leading to cardiovascular diseases." (PMID 34336955, 2021). "Therefore, ω3FAs may reduce the risk of cardiovascular diseases and the CRP level through their anti-inflammatory effects even in apparently healthy people." (PMID 33498799, 2021). "However, it is uncertain whether CRP is a marker of CVD risk or if it is causally related to cardiovascular disease." (PMID 33033455, 2020). "CRP levels have been linked to prognosis in patients with atherosclerotic disease, congestive heart failure, atrial fibrillation, myocarditis, aortic valve disease, and heart transplantation, suggesting that it has an active role in the pathophysiology of cardiovascular disease." (PMID 29706967, 2018). "Since CRP levels are linked to cardiovascular disease, which is also a risk factor for AD, our results indicate that chronic low-grade inflammation may play an early role leading to AD in ApoE4 carriers independent from cardiovascular diseases." (PMID 30646251, 2018). "In addition to proteins well known to be related to the risk of mortality and cardiovascular disease (e.g., CRP, adiponectin, angiotensinogen, and prothrombin), a variety are involved in inflammation, as well as others related via as of yet unknown mechanisms." (PMID 29399943, 2018). "C-reactive protein (CRP) may be causative in cardiovascular disease." (PMID 30533227, 2018). "Since quite ago, it is known that anti-inflammatory agents may have clinical benefits in preventing cardiovascular disease, in view of the direct relation existing between markers of a general inflammatory status, like C-reactive protein, and the risk of cardiovascular diseases." (PMID 26122487, 2016). "Moreover, even a tiny increase in the CRP level may point to an increased risk of cardiovascular disease (CVD) since atherosclerosis is a chronic inflammation of the cardiac wall." (PMID 26690167, 2015). "Thus, CRP is one of the most well-documented emerging cardiovascular disease risk factors." (PMID 23690772, 2013). "In current experiment, CRP significantly increased in hypercholesterolemic rabbits while there was no significant change in control group.CRP has not only been proposed as risk factors of cardiovascular disease, but has also been associated with the variables of insulin resistance syndrome." (PMID 23497719, 2012). "Systemic production of IL-6 could induce the acute phase response in liver, which entails the production of pro-coagulant factors such as plasminogen activator inhibitor 1 and antimicrobials such as C-reactive protein, whose increased concentrations have been associated with cardiovascular disease." (PMID 21054880, 2010). "CRP concentrations association with albuminuria may be affected by ethnicity and sex and this may part of the clustering of cardiovascular risk factors and the higher incidence of cardiovascular disease observed in African Americans." (PMID 20078870, 2010). "Therefore, long-term sleep restriction may lead to persistent changes in the immune system and the increased production of IL-17 together with CRP may increase the risk of developing cardiovascular diseases." (PMID 19240794, 2009). "Thus, it may be concluded from the present study that C-reactive protein and IL-6 have potential utility as risk markers for cardiovascular disease in the study population." (PMID 20407653, 2009).
cardiovascular disease (continued). "Across the different cardiovascular disease manifestations, a common pathogenic feature is HIV‐associated inflammation, including elevated biomarkers of systemic inflammation (e.g., CRP and IL‐6) and monocyte activation." (PMID 41489606, 2026). "The clinical relevance of HIT potentially lies in its ability to reduce CRP levels, a key factor given CRP’s established role as an independent predictor of cardiovascular disease in adults and a valuable tool for early diagnosis in pediatric populations." (PMID 41590696, 2026). "CRP has long been used as an inexpensive and accessible biochemical indicator of systemic inflammation in many forms of cardiovascular disease." (PMID 41596517, 2026). "CRP is a general inflammatory parameter and one of the most sensitive predictors of cardiovascular diseases." (PMID 40486662, 2025). "CRP is the main marker of systemic low-grade inflammation in patients with metabolic and cardiovascular disorders." (PMID 41300953, 2025). "In patients with established cardiovascular disease (CVD), elevated levels of CRP were independently linked to a higher long-term risk of developing HF." (PMID 40375290, 2025). "C-reactive protein (CRP) is the standard clinical marker for chronic low-grade inflammation and is an independent risk factor for cardiovascular disease (CVD)." (PMID 39940348, 2025). "Particularly in cardiovascular disease diagnosis, high-sensitivity CRP is considered one of the key indicators for predicting the risk of cardiovascular events." (PMID 39996992, 2025). "Blood biomarkers particularly CRP and Troponin I demonstrate strong potential as reliable measures of cardiovascular disease riskstatus." (PMID 40978648, 2025). "Carboxylated CNF-basedimmunosensors were developed for detecting C-reactive protein (CRP),an important marker for inflammation and cardiovascular disease." (PMID 41370747, 2025). "CRP is well known as an important biomarker for inflammation and cardiovascular disease, similar to Hcy." (PMID 40868071, 2025). "A systematic review examining the relationship between salivary biomarkers and cardiovascular diseases (CVDs) found that salivary C-reactive protein (CRP) shows consistent increases in CVD patients." (PMID 39958008, 2025). "The recent 2025 statement from the American College of Cardiology (ACC) on inflammation and cardiovascular disease recommends hs-CRP measurement as part of CVD primary prevention, reinforcing the clinical relevance of inflammation as a modifiable risk factor." (PMID 41341825, 2025). "Certain biomarkers, such as high-sensitivity C-reactive protein (hs-CRP) and Hemoglobin A1c (HbA1c), also called glycated hemoglobin, have demonstrated their ability to forecast cardiovascular diseases (CVDs) in people with DM." (PMID 41441018, 2025). "Multiple studies have shown that in SARS-CoV-2 patients with cardiovascular disease, elevated markers of thrombo-inflammatory activation like CRP, IL-6, and troponins are predictors of mortality." (PMID 40951379, 2025). "Levels of CRP have been correlated with cardiovascular diseases; thus, quantification of CRP has also been utilized for diagnostic reasons and follow-ups." (PMID 40310130, 2025). "CRP is a valuable clinical marker of inflammation, and an elevated CRP level is recognized as a robust independent predictor of cardiovascular disease (CVD)." (PMID 40330210, 2025). "Due to its capability to detect very low concentrations, the hs-CRP examination is well known to be a prognostic biomarker in various cardiovascular diseases, while CRP is more specifically used to diagnose infectious diseases." (PMID 41323643, 2025). "C-reactive protein (CRP) is a well-validated marker of systemic inflammation that has been extensively studied in cardiovascular diseases and, in particular, AMI." (PMID 41227029, 2025).
cardiovascular disease (continued). "Low serum EPA/arachidonic acid levels are reportedly associated with an increased risk for cardiovascular disease, and oral EPA has been shown to reduce cardiovascular risk and to lower both C-reactive protein (CRP) and low-density lipoprotein (LDL) levels." (PMID 40539061, 2025). "Uric acid (UA), albumin (Alb), and C-reactive protein (CRP) have been studied for their pathophysiological relevance in cardiovascular disease." (PMID 41323647, 2025). "Serum HP, CRP, B9, and B12 serve as indicators of various physiological processes and health conditions, including inflammation disorders, infections, hepatic and cardiovascular diseases, as well as the synthesis of neuroactive compounds." (PMID 39858234, 2025). "Existing research indicates that robotic surgery results in less intraoperative blood loss and lower postoperative levels of C-reactive protein (CRP), a sensitive inflammatory marker linked to cardiovascular disease." (PMID 41293736, 2025). "Although there is heterogeneity in the predictive value of CRP, the general consensus acknowledges a relation between CRP and cardiovascular disease." (PMID 40943791, 2025). "Univariate regression analysis revealed that age, sex, cardiovascular disease, COPD, delayed diagnosis, surgical delay, white blood cell, CRP, BUN, and RAR were associated with a significantly higher risk of developing major complications." (PMID 39993970, 2025). "C-reactive protein (CRP) has long been recognized as a biomarker of systemic inflammation and cardiovascular disease (CVD) risk." (PMID 40725102, 2025). "Adjusted for time-weighted average ­HbA1c, age, sex, cardiovascular disease history, BMI, hemoglobin, albumin and C-reactive protein." (PMID 41282290, 2025). "Inflammatory markers like white blood cell (WBC), C-reactive protein (CRP), and interleukin-6 (IL-6) are strongly linked to cardiovascular disease." (PMID 40190468, 2025). "Previous studies have indicated that the neutrophil-to-lymphocyte ratio (NLR) and C-reactive protein (CRP) are important indicators of cardiovascular risk and can be used to enhance risk stratification in patients with various cardiovascular diseases." (PMID 40182426, 2025). "Low levels of CRP can be assessed with the high-sensitivity CRP (hsCRP) test which has been shown to be useful as marker for cardiovascular disease." (PMID 41284612, 2025). "One study completed on a HD population concluded that the probability of cardiovascular disease almost doubles when the serum CRP levels are greater than 0.6 md/dL." (PMID 41342048, 2025). "Firefighters have been found to have elevated levels of inflammatory markers, including interleukin-6 (IL-6) and C-reactive protein (CRP), which are associated with an increased risk of metabolic and cardiovascular disorders." (PMID 40407432, 2025). "As a biomarker of cardiovascular disease, the CRP/HDLc ratio was significantly lower for asymptomatic than symptomatic patients (4.00 [1.43–10.1] vs. 10.5 [5.03–19.5], p = 0.004)." (PMID 40725264, 2025). "The oral frailty group was significantly older and had slower gait speed, fewer teeth, higher intact parathyroid hormone, higher C-reactive protein, higher frequency of cardiovascular disease, and lower employment at baseline." (PMID 40573061, 2025). "In conclusion, CRP contributes to cardiovascular disease by several mechanisms that require an in-depth analysis." (PMID 40282303, 2025). "Inflammatory indicators, including neutrophil count and high-sensitivity C-reactive protein (hs-CRP) levels, have demonstrated predictive value for long-term prognosis in cardiovascular disease patients." (PMID 40276550, 2025). "In the research field of cardiovascular diseases, studies on serum UAR and CRP as risk factors have been increasing." (PMID 41323647, 2025). "In this study, the interaction between GRS and PDI was performed on some predictive factors of cardiovascular diseases, such as C-reactive protein, plasminogen activator inhibitor 1, and insulin." (PMID 40628909, 2025).